OIP5 (Opa interacting protein 5)
Description:
Required for recruitment of CENPA to centromeres and normal chromosome segregation during mitosis.
Synonyms: CT86; MIS18B; hMIS18beta; 5730547N13Rik; LINT-25; MIS18beta
Tractability: PROTAC: ubiquitination databases record sites on it.
Gene: Protein-coding gene on chromosome 15 (41,309,268 to 41,332,595, reverse strand). Ensembl gene ENSG00000104147.
Subcellular location: Nucleus; Chromosome; Chromosome, centromere
Subcellular location (Human Protein Atlas): Nuclear speckles; Vesicles
Pathways (Reactome):
Cell Cycle: Deposition of new CENPA-containing nucleosomes at the centromere
Gene Ontology:
Molecular function: identical protein binding; protein binding
Biological process: cell communication; CENP-A containing chromatin assembly
Cellular component: Cajal body; CENP-A recruiting complex; chromatin; nuclear speck; nucleus; chromosome, centromeric region; nucleoplasm; chromocenter; chromosome
Genetic constraint (gnomAD): Loss-of-function variants: 20 observed, 16.34 expected, observed/expected ratio (o/e) 1.22, 90% interval 0.86 to 1.74. The upper end of that interval is the gene's LOEUF score, 1.74, which puts it in group 6 of 6, group 1 being the genes least tolerant of losing a copy. Missense variants: 267 observed, 234.83 expected, observed/expected ratio (o/e) 1.14, 90% interval 1.03 to 1.26. Synonymous variants: 119 observed, 105.22 expected, observed/expected ratio (o/e) 1.13, 90% interval 0.97 to 1.32.
Homologues: Orthologues: chimpanzee OIP5 (99% identical), macaque OIP5 (94% identical), pig OIP5 (83% identical), dog OIP5 (82% identical), rabbit OIP5 (74% identical), guinea pig OIP5 (68% identical), rat Oip5 (66% identical), mouse Oip5 (65% identical), tropical clawed frog oip5 (28% identical), zebrafish oip5 (22% identical). Paralogues in human: MIS18A (19% identical).
Diseases named in the same sentence as OIP5 in open-access papers:
OIP5 is named in the same sentence as 49 diseases in open-access papers, as found by Europe PMC text mining. Sharing a sentence is not in itself a finding about the gene and the disease. The quoted sentences say what the papers report.
breast carcinoma (8 papers, 2016 to 2024). "Another study showed that the knockdown of Linc-OIP5 suppressed the angiogenesis of the HUVECs through YAP1/Notch/NRP1 signalling in breast cancer." (PMID 39219375, 2024). "The knockdown of OIP5 has been shown to trigger G1 arrest-dependent apoptosis and reduce cell proliferation in breast cancer cells." (PMID 38474305, 2024). "Previous studies have shown that OIP5 is highly expressed in various human malignant tumors, such as breast cancer, malignant glioma, liver cancer, and bladder cancer, and can cause corresponding immune responses in tumor patients." (PMID 37660035, 2023). "After knocking down linc-OIP5 in breast cancer cells, JAG1 expression was downregulated while DLL4 expression was upregulated in co-cultured HUVECs, rendering the production of fewer blood vessels." (PMID 32046779, 2020). "The sum of our results delineated that linc-OIP5 in breast cancer cells may act on the upstream of YAP1/Notch/NRP1 signaling circuit associated with tube formation abilities of HUVECs through an indirect cell–cell contact." (PMID 32046779, 2020). "Here, we aimed to investigate whether linc-OIP5 in breast cancer cells affects the angiogenesis of HUVECs and whether the linc-OIP5 regulations are involved in angiogenesis-related Notch and Hippo signaling pathways." (PMID 32046779, 2020). "The CT genes, OIP5, TAF7L, and AURKC have been identified as biomarkers for breast cancer and may be promising and potent candidates for therapeutic cancer vaccines." (PMID 36967804, 2023). "There were negative expression correlations of hsa-let-7a-5p-CCNB2, hsa-let-7c-5p-CCNB2, hsa-let-7a-5p-AURKB, hsa-miR-30a-5p-CDC20, hsa-miR-30a-5p-MYBL2, hsa-miR-29c-3p-OIP5, hsa-miR-10b-5p-CHAF1B, hsa-miR-195-5p-CCNE1, and hsa-miR-497-5p-CCNE1 in ERα positive breast cancer." (PMID 32500028, 2020). "Notably, OIP5 has been previously reported to be highly expressed in various cancers, including CRC, hepatocellular carcinoma, renal cell carcinoma, bladder cancer, breast cancer, and glioma." (PMID 38474305, 2024).
colorectal cancer (8 papers, 2014 to 2025). A primary or metastatic malignant neoplasm that affects the colon or rectum. "Aberrant expression of OIP5 has been reported in several types of cancer cells and is associated with poor patient prognosis in colorectal cancer, gastric cancer, esophageal cancer, and lung cancer." (PMID 36345848, 2023). "This study leveraged computational immuno-informatics tools to identify high-affinity HLA class I-restricted epitopes from DKKL1, FBXO39, and OIP5, providing a basis for the development of a peptide-based vaccine for colorectal cancer immunotherapy." (PMID 40599850, 2025). "This study identified CTL-specific epitopes from DKKL1, FBXO39, and OIP5 as potential targets for colorectal cancer immunotherapy." (PMID 40599850, 2025). "In view of this, the present study aims to identify lead CTL epitopes targeting DKKL1, FBXO39, and OIP5 CTAs for colorectal cancer." (PMID 40599850, 2025). "Abundant expression of OIP5 is observed in cancer cells such as esophageal cancer, gastric cancer, colorectal cancer, lung cancer, renal cell carcinoma, and acute myeloid leukemia." (PMID 24516558, 2014). "In colorectal cancer, CTAs such as DKKL1, FBXO39, and OIP5 hold great promise as therapeutic targets due to their overexpression and immunogenic properties." (PMID 40599850, 2025). "Opa interacting protein 5 (OIP5) was a member of cancer-testis antigen (CTA) family, which might be a novel therapeutic target for cancer therapy because of the high expression of this gene in colorectal cancer 49, lung cancer 50, and esophageal cancer." (PMID 32194788, 2020).
esophageal cancer (7 papers, 2013 to 2023). A primary or metastatic malignant neoplasm involving the esophagus. "The other group also showed the high expression level of OIP5 in lung and esophageal cancers by using cDNA microarray analysis and furthermore demonstrated that OIP5 expression level was significantly associated with poor prognosis of these patients." (PMID 24516558, 2014). "Given the limited evidence for the association of OIP5 with oncogenic events, the mechanisms of OIP5-promoted tumorigenesis in esophageal cancer needs to be further investigated." (PMID 36661650, 2022). "Our study demonstrated for the first time that OIP5 promotes the occurrence and development of esophageal cancer cells by mediating intracellular lipid metabolism." (PMID 36661650, 2022). "Reportedly, OIP5 also has some prognostic value, and its expression paralleled a poor prognosis in nonsmall cell lung cancer and esophageal cancer." (PMID 27635108, 2016). "Previous studies have demonstrated high expression of OIP5 mRNA in gastric, colorectal, lung and esophageal carcinomas, where it contributes to the growth of cancer cells." (PMID 23592437, 2013). "Previous work demonstrated that the expression level of OIP5 was elevated in NLCSC and esophageal cancer tissues, and silencing of OIP5 could suppress tumor cell growth." (PMID 34434213, 2021). "Moreover, the expression level of OIP5 was closely related to the prognosis of NLCSC and esophageal cancer and was an independent prognostic factor for LUAD." (PMID 34434213, 2021).
gastric cancer (6 papers, 2014 to 2024). A primary or metastatic malignant neoplasm involving the stomach. "In gastric carcinoma, OIP5.AS1 regulates PI3K/AKT and Wnt/β-catenin pathways in a High Mobility Group AT-Hook 2 (HMGA2)-dependent way32." (PMID 38326441, 2024). "For instance, in case of gastric cancer, the expression of CCNB2, OIP5 etc. genes were found to be altered along with MTUS1 mutation." (PMID 34125870, 2021). "OIP5 was identified among the up-regulated genes in gastric cancer cells by using cDNA microarray analysis." (PMID 24516558, 2014). "Moreover, Opa-interacting protein 5 (OIP5) overexpression prevented docetaxel-induced cell death in gastric cancer cells by activating MFN2/PINK1-mediated mitophagy." (PMID 31121959, 2019).
hepatocellular carcinoma (6 papers, 2017 to 2024). A malignant tumor that arises from hepatocytes. "In hepatocellular carcinoma, OIP5 activates AKT oncogenic signaling and enhances cancer cell metastasis." (PMID 36345848, 2023). "The downregulation of OIP5 was achieved by regulating mTORC1 and the β- catenin signaling pathway inhibited the growth and metastasis of hepatocellular carcinoma." (PMID 37660035, 2023). "Despite the availability of a considerable amount of data, the precise function of OIP5 in human cancer, particularly hepatocellular carcinoma (HCC), remains unclear." (PMID 28184024, 2017). "Consequently, the occurrence and development of cirrhosis and hepatocellular carcinoma may be regulated by 1700020I14Rik- Oip5 and-Chp interactions." (PMID 29383134, 2017). "Opa interacting protein 5 (OIP5) is upregulated in some types of human cancers, but the biological implications of its upregulation have not yet been clarified in human hepatocellular carcinoma (HCC)." (PMID 28184024, 2017).
lung carcinoma (6 papers, 2014 to 2023). "In addition to lung cancer, the expression level of OIP5 is also increased in nasopharyngeal carcinoma, and its knockout inhibits ability of the proliferation, migration, and invasion of tumor cells." (PMID 34434213, 2021). "OIP5 (Opa interacting protein 5), one of the cancer-testis antigens, is involved in cell cycle regulation and interacts with RAF1 in lung cancer, resulting in poor prognosis." (PMID 36498802, 2022).
glioblastoma (5 papers, 2013 to 2024). The most malignant astrocytic tumor (WHO grade IV). "In glioblastoma, cells exhibit obvious reduction of division when OIP5 is knocked down, whereas its recovery enhances proliferation ability." (PMID 37292517, 2023). "Under abnormal condition, OIP5 is involved in a variety of diseases, including colorectal cancer, gastric cancer, lung cancer, bladder cancer, and glioblastoma." (PMID 37292517, 2023). "Aberrant OIP5 expression is common in various types of cancer, including glioblastoma, bladder, esophagus, breast, gastric, colorectal, and liver cancer." (PMID 36661650, 2022). "In contrast, few CTAs have been correlated with a better prognosis such as ACTL8, OIP5, XAGE3 and CTCFL in glioblastoma." (PMID 38596293, 2024).
nasopharyngeal carcinoma (4 papers, 2021 to 2024). A carcinoma arising from the nasopharyngeal epithelium. "Thus, OIP5 appears to promote nasopharyngeal carcinoma progression by modulating the JAK2-STAT3 signaling pathway." (PMID 38474305, 2024). "Previous research revealed that OIP5 could promote metastasis of nasopharyngeal carcinoma cells by promoting EMT via modulation of JAK2/STAT3 signal." (PMID 35242130, 2022). "Additionally, OIP5 KD has been observed to inhibit epithelial–mesenchymal transition (EMT) and downregulate phosphorylated JAK2 and phosphorylated STAT3 in the JAK2-STAT3 pathway in nasopharyngeal carcinoma." (PMID 38474305, 2024).
bladder cancer (3 papers, 2021 to 2024). "OIP5 was reported to be a component gene in a multigene set predicting the risk of prostate cancer recurrence; its upregulation associates with adverse features in ccRCC and bladder cancer, supporting a general involvement of OIP5 in urogenital cancers." (PMID 34503297, 2021). "Functionally, knockdown of OIP5 was reported to attenuate the proliferation of bladder cancer cells, as well as colorectal and gastric cells in vitro." (PMID 34503297, 2021).
esophageal squamous cell carcinoma (3 papers, 2016 to 2025). Esophageal squamous cell carcinoma (ESCC) is a type of esophageal carcinoma (EC) that can affect any part of the esophagus, but is usually located in the upper or middle third. "OIP5 is a tumor-promoting factor of esophageal squamous cell carcinoma cells, which can promote the occurrence and development of esophageal squamous cell carcinoma." (PMID 36661650, 2022). "This suggests that the central gene OIP5 may affect the fatty acid metabolism of esophageal squamous cell carcinoma and the occurrence and development of esophageal squamous cell carcinoma." (PMID 36661650, 2022). "The expression status and biological function of OIP5 in esophageal squamous cell carcinoma and the exact mechanism of OIP5 have not been well studied." (PMID 36661650, 2022). "However, the effect of OIP5 on fatty acid metabolism in esophageal squamous cell carcinoma has not been investigated." (PMID 36661650, 2022).
liver cancer (3 papers, 2022 to 2024). An epithelial or non-epithelial malignant neoplasm that arises from the liver. "In liver cancer, OIP5 knockdown upregulates BMPR2 expression to inhibit the progression of liver cancer, suggesting an anticancer role for BMPR2 in liver cancer." (PMID 38538669, 2024). "For example, overexpression of OIP5 can promote the proliferation of liver cancer cells and inhibit their apoptosis." (PMID 37660035, 2023).
lung adenocarcinoma (3 papers, 2024 to 2025). A carcinoma that arises from the lung and is characterized by the presence of malignant glandular epithelial cells. "Other bimodally expressed genes identified in our analyses, such as FOXM1, MELK, RGS20, and OIP5, have been previously reported to associate with clinical outcomes and play functionally significant roles in lung adenocarcinoma." (PMID 40427178, 2025). "Cell cycle-related genes (BIRC5, OIP5, and CDCA3, etc.)were specifically upregulated in PTPRT-low lung adenocarcinoma (LUAD)." (PMID 38216925, 2024).
Obesity (3 papers, 2014 to 2019). Accumulation of substantial excess body fat. "Moreover, Oip5 was previously proved to be associated with adipose proliferation and was found up regulated in obesity." (PMID 29383134, 2017). "Insulin and TNF-α, those are augmented in obesity, increased Oip5 mRNA level, suggesting that such obesity-related signals increase the number of preadipocytes partly through Oip5 and provide new adipocytes for fat storage to maintain energy balance in a whole body." (PMID 24516558, 2014). "In a series of studies, Opa (Neisseria gonorrhoeae opacity-associated)-interacting protein 5 (OIP5) was nominated as a molecule of unknown function in adipocytes and thus the present study was performed to investigate the role of OIP5 in obesity." (PMID 24516558, 2014). "Present study suggested that the increased Oip5 in obese adipose tissues might promote the proliferation of preadipocytes and accelerate the development of obesity." (PMID 24516558, 2014). "Oip5 is expected as a new therapeutic target of obesity and type 2 diabetes." (PMID 24516558, 2014).
cervical carcinoma (2 papers, 2018 to 2020). A carcinoma arising from either the exocervical squamous epithelium or the endocervical glandular epithelium. "OIP5-AS1is reported to reduce proliferation of cervical cancer by serving as a sponge ceRNA for HuR and ranked 10th by CLING." (PMID 32211391, 2020). "As a homologous gene of 1700020I14Rik, OIP5-AS1was reported to reduce cell proliferation by serving as a sponge or a ceRNA for HuR in human cervical carcinoma HeLa cells." (PMID 29700282, 2018).
glioma (2 papers, 2021 to 2024). A benign or malignant brain and spinal cord tumor that arises from glial cells (astrocytes, oligodendrocytes, ependymal cells). "Linc-OIP5 lncRNA is upregulated in glioma tissue and positively correlates with glioma grade." (PMID 34316694, 2021).
Azoospermia (1 paper, 2023). Absence of any measurable level of sperm,whereby spermatozoa cannot be observed even after centrifugation of the semen pellet. "Collectively, these results implicate that OIP5 interacts with NCK2 to modulate human SSC self-renewal and apoptosis via cell cyclins and cell cycle progression and that its mutation and/or lower expression is correlated with azoospermia." (PMID 37292517, 2023). "Significantly, whole-exome sequencing of 777 patients with nonobstructive azoospermia (NOA) revealed 54 single-nucleotide polymorphism mutations of the OIP5 gene (6.95%), while the level of OIP5 protein was obviously lower in testes of NOA patients compared to fertile men." (PMID 37292517, 2023). "RT-PCR and qPCR demonstrated the level of OIP5 mRNA was significantly lower in spermatocyte maturation arrest (Spc MA) and Sertoli-cell-only syndrome (SCOS) than obstructive azoospermia patients." (PMID 37292517, 2023). "We also measured the expression levels of OIP5 in testis tissues from NOA patients and obstructive azoospermia patients with normal spermatogenesis." (PMID 37292517, 2023). "Moreover, we revealed that mutation or lower expression of OIP5 might be associated with nonobstructive azoospermia (NOA)." (PMID 37292517, 2023).
colorectal tumor (1 paper, 2024). "In conclusion, MISP enhances colorectal tumorigenesis through its interaction with OIP5 and stimulates colorectal tumor growth by upregulating the levels of phosphorylated STAT3 in the JAK2-STAT3 signaling pathway." (PMID 38474305, 2024).
Fanconi anemia (1 paper, 2022). Fanconi anemia (FA) is a hereditary DNA repair disorder characterized by progressive pancytopenia with bone marrow failure, variable congenital malformations and predisposition to develop hematological or solid tumors. "The KEGG results suggested that OIP5 may regulate immunity through Homologous recombination, Human T−cell leukemia virus 1 infection, Fanconi anemia pathway and Nucleotide excision repair signaling pathway." (PMID 35242130, 2022).
Immunodeficiency (1 paper, 2022). Failure of the immune system to protect the body adequately from infection, due to the absence or insufficiency of some component process or substance. "Further, a KEGG pathway analysis of OIP5-associated immunomodulators showed that the primary immunodeficiency pathway, the JAK-STAT signaling pathway, the T cell receptor signaling pathway and the NF-kappa B signaling pathway might be involved in OIP5-mediated immune response." (PMID 35242130, 2022).
infiltrating ductal carcinoma (1 paper, 2024). "Notably, the expression of PINK1.AS, OIP5.AS1, HID.AS1, and MAPT.AS1 was statistically higher in the infiltrating ductal carcinoma subtype." (PMID 38326441, 2024).
lentivirus infection (1 paper, 2023). Virus diseases caused by the Lentivirus genus. "For this reason, siRNA lentivirus infection was used to knock down the expression of OIP5 in A2780 cells." (PMID 37660035, 2023). "Subsequently, the OIP5 gene was knocked down by siRNA lentivirus infection." (PMID 37660035, 2023).
leukaemia (1 paper, 2021). "Even though RAF is not significantly differentially expressed in the leukaemia signature itself, it is the first neighbour of significantly differentially expressed genes of the disease, such as PBK, OIP5 and CDC25A, and may thereby exert indirect effects on the system." (PMID 34131166, 2021).
lymph node metastasis (1 paper, 2021). "OIP5 expression is significantly upregulated in pRCC; high levels of OIP5 correlate with adverse clinical characteristics of the disease, including stage, histological subtype (T2P), molecular subtype (CIMP), and lymph node metastasis." (PMID 34503297, 2021).
male infertility (1 paper, 2023). The inability of the male to effect fertilization of an ovum after a specified period of unprotected intercourse. "More importantly, we have revealed that OIP5 mutation and/or abnormal expression may be related to male infertility." (PMID 37292517, 2023). "We finally probed whether OIP5 was associated with male infertility." (PMID 37292517, 2023).